MMP9 (matrix metallopeptidase 9)
Diseases named in the same sentence as MMP9 in open-access papers (continued):
Sharing a sentence is not in itself a finding about the gene and the disease.
rheumatoid arthritis (continued). "Moreover, MMP-2 and MMP-9 are involved in inflammatory joint diseases, including rheumatoid arthritis, through degradation of cartilage and joint tissues." (PMID 38069361, 2023). "Elevated MMP-9 levels can be found in cases of rheumatoid arthritis." (PMID 37446715, 2023). "Upregulated chymase and MMP-9 have been observed in tissues from patients and animal models of aortic aneurysm, inflammatory gastrointestinal and hepatic diseases, acute pancreatic failure, atopic dermatitis and rheumatoid arthritis." (PMID 36289761, 2022). "Additionally, miR-145-5p aggravates rheumatoid arthritis (RA) by activating the NF-κB pathway and enhances the secretion of matrix metalloproteinase-9 (MMP-9)." (PMID 35094651, 2022). "MMP-9 is upregulated in the synovial fluid in patients with rheumatoid arthritis." (PMID 36289761, 2022). "Therefore, the expression of MMPs, such as MMP-1 and/or MMP-9, can be epigenetically regulated in multiple diseases influenced by HDACs including inflammatory conditions such as rheumatoid arthritis, bacterial infections, and cancer metastasis." (PMID 33920915, 2021). "It has been reported that CCR3 expression was increased under rheumatoid arthritis conditions, and it mediated eotaxin-1 induced matrix metalloproteinase (MMP)-9 upregulation in fibroblast-like synoviocyte which may further result in articular damage." (PMID 30972099, 2019). "Notably, expression of both MMP-9 and MMP-2 is enhanced in the joints of patients with rheumatoid arthritis, while MMP-9 is overproduced in the osteoarthritic bone tissue." (PMID 29137306, 2017). "The finding that rhIL-6 increased the production of MMP-9 by human immortalized chondrocyte cell lines may have important implications with respect to the destruction of articular cartilage in rheumatoid arthritis and osteoarthritis." (PMID 27398263, 2016). "Indeed, they indicated that SF levels of MMP-9 were higher in rheumatoid arthritis patients compared to osteoarthritis." (PMID 27478294, 2016). "Interestingly, MMP-9 inhibitors may be helpful in some autoimmune diseases, such as rheumatoid arthritis." (PMID 37569509, 2023). "The plasma level as well as the activity of the MMP-9 in PsA is higher than in PsV, which makes the symptoms of this disease closer to that of rheumatoid arthritis (RA)." (PMID 34691360, 2021). "Furthermore, MMP9 expression is elevated in rheumatoid arthritis and focal brain ischemia." (PMID 32256671, 2020). "Andrographolide reduces MMP-1, MMP-3, and MMP-9 expression of rheumatoid arthritis fibroblast-like synoviocytes (RA-FLS) in hypoxia, decreasing HIF-1α expression and interfering with HIF-1α binding to DNA." (PMID 33374961, 2020). "As in rodent models of rheumatoid arthritis, inhibition of matrix metalloproteinases may have also played a protective role in LPS-induced lung injury that is also characterized by a marked increase of MMP9 in the lung." (PMID 21034489, 2010). "The inflammatory targets that mediate rheumatoid arthritis mainly include (TNF, PTPN11, IL6, etc.); the main targets that mediate RA oxidative stress are NOS3; the targets that mediate the destruction of extracellular matrix tissue in RA mainly include (MMP9, MMP2, ANXA5, etc.)." (PMID 38238321, 2024). "In a recent study, researchers inhibited the secretion of MMP9, thus suppressing bone resorption by targeting ATP5B, providing new insight into protecting bones in rheumatoid arthritis (RA)." (PMID 38017559, 2023). "Taking clues from other inflammatory diseases of the joint such as rheumatoid arthritis (RA) and osteoarthritis (OA), infiltration of CD206+, FRβ+, CD163+, MMP-9+ and iNOS+ macrophages has been reported." (PMID 35733858, 2022). "Matrix metalloproteinase-9 (MMP9) played a critical role in degrading components of extracellular matrix (ECM) and leukocyte migration in rheumatoid arthritis patients." (PMID 35127697, 2021).
rheumatoid arthritis (continued). "Another of our previous studies, on rheumatoid arthritis, found that inhibition of LOX expression in rat synovial fluid can downregulate MMP-2 and MMP-9 expression." (PMID 31777578, 2019). "The suppressive role of MMP-2 and a pivotal role of MMP-9 in the development of inflammatory joint disease was described in rheumatoid arthritis and other studies support this antagonistic role of MMP-2 and MMP-9 in inflammation." (PMID 28118356, 2017). "In monocytes from patients with rheumatoid arthritis, inhibition of extracellular signal-regulated kinase (ERK) abolished Cyclosporine A-induced MMP-9 expression." (PMID 19272186, 2009). "Immunohistochemical staining of rheumatoid nodules has shown positive staining of epithelioid cells for HLA-DR, CD68, lysozyme, MMP-2, MMP-3, MMP-9 and Ki67." (PMID 19604347, 2009). "IL-1β increased the transcriptional and translational levels of MMP-1 and MMP-13 in rheumatoid arthritis FLSs, whereas the levels of MMP-2 and MMP-9 were unaffected." (PMID 17697361, 2007). "Cipemastat, which inhibits MMP-1, MMP-3, and MMP-9, was used for the treatment of rheumatoid arthritis and osteoarthritis, but it was not shown to prevent the progression of joint damage in patients." (PMID 33419373, 2020). "Recent proteomic studies have identified MMP-9 as a disease activity marker in ANCA-associated vasculitis, but not in patients with rheumatoid arthritis or systemic erythematosus." (PMID 31798577, 2019). "Additionally, our previous study on rheumatoid arthritis also found that LOX expression levels in synovial fluid were positively correlated with the expression levels of MMP-2 and MMP-9." (PMID 31777578, 2019). "The finding that TCZ suppressed rhIL-6-mediated MMP-9 production suggests that TCZ, currently employed in the medical therapy of rheumatoid arthritis, could be considered as a drug for osteoarthritis." (PMID 27398263, 2016). "In vitro experiments have shown that the JBQG drug serum can inhibit the expression of cytokines (IL-6, IL-8, IL-22, IL-23), chemokine proteins and mRNA expression (MMP-1, MMP-2, MMP-3, MMP-9, MMP-13) in rheumatoid arthritis synovial fibroblasts (RA-FLS)." (PMID 37180723, 2023). "All MMP-9 and MMP-2 proteoforms were identified in archival synovial fluids with the use of zymography analysis and the levels of MMP-9 versus MMP-2 were studied in various arthritic diseases, including rheumatoid arthritis (RA)." (PMID 34912337, 2021). "This might also apply to the origin of the cells, as a prior study in fibroblast-like synoviocytes derived from rheumatoid arthritis patients found that IL-6 protein and mRNA for MMP-9, but not other MMPs, were upregulated by LIGHT." (PMID 29616048, 2018). "Rheumatoid arthritis (RA) is characterized by increases in MMP-2, MMP-3, and MMP-9." (PMID 36830637, 2023). "As MMP-9 plays a role in tissue remodeling during physiologic and pathologic processes by initiating the degradation of the ECM, the over expression of MMPs might lead to tissue destruction that is characteristic of chronic inflammatory diseases such as COPD, rheumatoid arthritis and scleritis." (PMID 24179443, 2013). "Gallic acid has been reported to induce apoptosis of rheumatoid arthritis (RA) fibroblast-like synoviocytes (FLS) by regulating the expression of apoptosis-related proteins and reducing the expression of pro-inflammatory mediators, such as pro-inflammatory cytokines, chemokines, COX-2 and MMP-9." (PMID 26107568, 2015). "This is consistent with a previous report showing that CypA increased MMP9, but not MMP2, expression via CD147 in rheumatoid arthritis." (PMID 23031673, 2012). "Similarly, previous studies reported a strong correlation between the expression of VEGF and MMP-9, but not with MMP-2, in cancer patients, and in the synovial fluid of patients with rheumatoid arthritis." (PMID 24392031, 2013).
Hyperglycemia (94 papers, 2010 to 2025). An increased concentration of glucose in the blood. "While hyperglycemia is traditionally implicated in impaired wound healing, our data imply that MMP-9 elevation operates through glycemia-independent pathways." (PMID 41189831, 2025). "Chronic hyperglycemia elevates ROS levels in tissues, which not only cause cellular damage but also perpetuate inflammation and activate matrix metalloproteinases like MMP-9." (PMID 41150817, 2025). "Sex-specific associations were observed with higher MMP-9 levels in diabetic females, as well as with higher HbA1c levels in males, together these associations stress a link between long-term hyperglycaemia and EVA." (PMID 34526107, 2021). "Furthermore, hyperglycemia-induced upregulation of retinal MMP-9 is associated with hypermethylation of H3K9 at the MMP-9 promoter, mediated by LSD1." (PMID 40589740, 2025). "Hyperglycemia enhances the expression of MMP-9 and NF-κB, undermining vascular wall integrity and increasing the probability of hematoma growth." (PMID 40385356, 2025). "In the context of DFUs, persistent hyperglycemia, and chronic inflammation have been shown to upregulate MMP-9 expression, leading to excessive ECM breakdown and impaired tissue regeneration." (PMID 40364880, 2025). "In the early stages of DKD, MMP-9 increases as an initial response to hyperglycemia and oxidative stress." (PMID 40422591, 2025). "Hyperglycemia increases oxidative stress and matrix metalloproteinase-9 (MMP-9) activity and leads to brain-blood-barrier dysfunction." (PMID 40739302, 2025). "Sustained hyperglycemia induces the synthesis of MMP-9, as evidenced by increased expression and activity of MMP-9 due to the oxidative stress generated in vascular endothelial cells." (PMID 39335666, 2024). "Pae inhibits MMP-9 expression and the inflammatory response in hyperglycemia-induced retinal microglia via inhibition of the TLR4/NF-κB signaling pathway, through the upregulation of suppressor of cytokine signaling 3 in diabetic retinopathy." (PMID 35184653, 2022). "Nevertheless, previous studies have shown that the increase of MMP2 and MMP9 activities is associated with the inflammatory process and oxidative stress in APP/PS1 mice and hyperglycemia alters the PKC-β pathway, causing an increase in MMP2." (PMID 36345028, 2022). "According to research, an increase in matrix metalloproteinase-9 (MMP-9) and tissue inhibitor of matrix metalloproteinase production is associated with an increase in BBB permeability brought on by hyperglycemia." (PMID 36678547, 2022). "Hyperglycaemia induced MMP-9 is inhibited by the administration of paeoniflorin via induction of SOCS3 (negative regulator of TLR signalling cascade), leading to inhibition of TLR4 signalling." (PMID 38983565, 2022). "A recent study found that MMP9 mediates hyperglycemia-induced hepatocyte pyroptosis, suggesting a role for MMPs in pyroptosis." (PMID 35705936, 2022). "Microglial matrix metalloproteinase 9 (MMP-9) levels are raised in response to hyperglycaemia via HMGB1/TLR4 signalling in BV2 murine glial cells." (PMID 38983565, 2022). "Hyperglycemia can upregulate MMP-9 expression in vascular endothelial cells by lowering H4K20me3, increasing Ac-H3K9, and promoting the recruitment of NF-κB subunit p65 at the promoter." (PMID 34394383, 2021). "Following STZ treatment (200 mg/kg, i.p.), 88.75% (n=80) of the MMP-9-/- mice developed hyperglycemia (vs. 86%, n=150 wild-type, WT) and 56.25% (n=80) of the MMP-9-/- mice developed mechanical allodynia (vs. 60.67%, n=150 WT)." (PMID 34631222, 2021). "Hyperglycemia has been shown to increase the activity of matrix metalloproteinase (MMP)-9 and MMP-3 in the ischemic region, exacerbate blood-brain barrier dysfunction and hemorrhagic transformation after recanalization." (PMID 35126278, 2021). "Our results show that hyperglycemia increases ROS production in hCSCs, which is prevented by targeted deletion of the MMP9 gene." (PMID 32170070, 2020).
Hyperglycemia (continued). "Altogether, we demonstrate the intracellular role of MMP9 in mediating acute hyperglycemia-induced cell death via apoptosis and pyroptosis in hCSCs." (PMID 32170070, 2020). "We found that hyperglycemia induced oxidative stress and increased cell death by promoting pyroptosis and apoptosis in hCSCs, which was prevented in MMP9−/− hCSCs." (PMID 32170070, 2020). "To investigate if MMP9 mediates hyperglycemia-induced ROS production in hCSCs, we treated hCSCs and MMP9−/− hCSCs with NG and HG for 24 h, and measured cellular levels of ROS by CellROX staining." (PMID 32170070, 2020). "To determine the role of MMP9 in hyperglycemia-induced pyroptosis of hCSCs, we incubated hCSCs and MMP9−/− hCSCs with NG or HG medium for 24 h, and measured the key molecular markers of pyroptosis." (PMID 32170070, 2020). "Taken together, we found that hyperglycemia upregulates oxidative stress-induced cell death via apoptosis and pyroptosis in hCSCs, which is mediated by MMP9." (PMID 32170070, 2020). "Our successful creation and validation of MMP9−/− hCSCs was important for determining the specific role of MMP9 in hyperglycemia-induced hCSCs death." (PMID 32170070, 2020). "To establish the role of MMP9 in hyperglycemia-induced hCSCs death, we created MMP9−/− hCSCs using the CRISPR-Cas9 technique." (PMID 32170070, 2020). "In the present study, we show that ablation of MMP9 prevents hyperglycemia-induced cell death via apoptosis and pyroptosis in hCSCs and improves viability of hCSCs." (PMID 32170070, 2020). "With respect to hyperglycemia, we previously showed that decreased MMP-9 expression and macrophage activation under hyperglycemic conditions correlated with suppression of aneurysm formation." (PMID 31546645, 2019). "Data from retinal capillary cells and diabetic mouse models have shown that hyperglycemia leads to MMP-9 promoter hypomethylated and the activation of the demethylation machinery, resulting in its increased transcription." (PMID 30987683, 2019). "Hyperglycemia in diabetic animals in vivo enhanced MMP9 expression compared with normoglycemic wounds." (PMID 28874756, 2017). "After induction by hyperglycemia, MMP-9 degraded the extracellular matrix, collagen IV, basement membrane, and TJ protein and enhanced BRB permeability." (PMID 28367226, 2017). "Using human retinal endothelial cells, and also retinal microvessels from diabetic rats, effect of hyperglycemia on H3K27me3, and recruitment of Ezh2 at the MMP-9 promoter were quantified by chromatin-immunoprecipitation technique." (PMID 29261844, 2017). "Studies performed in human cadaver eyes confirmed that hyperglycemia caused H3K9 acetylation in MMP-9 (Ac-H3K9), and p65 activation resulted in CpG methylation within MMP-9." (PMID 28815013, 2017). "Hyperglycemia elevated H3K27me3 levels and the recruitment of Ezh2 at the MMP-9 promoter, and increased the enzyme activity of Ezh2." (PMID 29261844, 2017). "The significant rise of MMP-9 across the BG groupings in this study cannot solely be attributed to acute (stress) or chronic hyperglycemia." (PMID 27110221, 2016). "To conclude, telmisartan works through PPARδ, instead of the AMPK pathway, to suppress the hyperglycemia-enhanced expression of STAT3/CTGF/MMP9 and the subsequent cardiac fibrosis (Graphic abstract)." (PMID 27519769, 2016). "Hyperglycemia-induced activation of MMP-9 promotes apoptosis of retinal capillary cells and can result in development of diabetic retinopathy." (PMID 27280065, 2016). "Suppression of hyperglycemia-induced activation of MMP-9 can ameliorate apoptosis of retinal capillary cells." (PMID 26692905, 2015). "It has been demonstrated that the circulating level of MMP-9 is increased under hyperglycemia condition." (PMID 26692905, 2015).
Hyperglycemia (continued). "In the diabetic retina, prolonged hyperglycemia and altered metabolic pathways increase oxidative stress, upregulate proinflammatory cytokines and chemokines, adhesion molecules, growth factors, and MMP-9, leading to the breakdown of the BRB." (PMID 39851513, 2025). "The inhibition of MMP9 improved cell survival and decreased apoptosis induced by hyperglycemia." (PMID 40563254, 2025). "Our previous observation that PMP (when incorporated into CRC cells) stimulate the metalloproteases MMP-2 and MMP-9 (which are able to degrade the extracellular matrix) may be consistent with the findings of studies focusing on hyperglycaemia." (PMID 40713559, 2025). "The activity of these transcription factors is enhanced under hyperglycemic conditions, suggesting that hyperglycemia may facilitate MMP-9 transcription to some extent." (PMID 39885987, 2024). "Hyperglycemia is also an important factor in promoting MMP-9 expression." (PMID 39885987, 2024). "Hyperglycemia disturbs trophoblast proliferation and invasion via inhibiting the epithelial-mesenchymal transition, altering the protein expression of related proteases (MMP9, MMP2, and uPA) and angiogenic factors (VEGF, PIGF)." (PMID 37091848, 2023). "In vivo experiments showed that hyperglycemia could activate MMP-9 under the action of AGEs and accelerate the apoptosis of retinal capillary cells." (PMID 35845597, 2022). "Herein, we demonstrate that hyperglycemia increased the level of MMP‐9, levels related to the disrupted BBB integrity in MCAO rats, which may allow opportunistic pathogens or the toxic products of gut microbiota to come in close proximity to the brain." (PMID 34591349, 2022). "Hyperglycemia may increase the activity of MMP9 and, therefore, provides growth space and nutrients for neovascularization by degrading the basement membrane and relaxing the cell structure." (PMID 33747106, 2021). "The synthesis of MMP-9 is induced by sustained hyperglycemia." (PMID 33419373, 2020). "To determine whether MMP9 mediates hyperglycemia-induced hCSCs death and if abrogation of MMP9 improves viability of hCSCs, we treated hCSCs and MMP9−/− hCSCs with NG or HG for 24 h." (PMID 32170070, 2020). "In the present study, we aim to investigate whether MMP9 is a mediator of hyperglycemia-induced cell death in human cardiac stem cells (hCSCs) in vitro." (PMID 32170070, 2020). "Hyperglycemia is thought to enhance matrix metalloproteinase‐9 (MMP‐9) activity in the ischemic area during reperfusion, which reduces a junctional protein in endothelial cells and then results in blood–brain barrier (BBB) damage (Kamada, Yu, Nito, & Chan, 2007)." (PMID 32697441, 2020). "In the present study, we sought to determine whether MMP9 mediates hyperglycemia-induced cell death via apoptosis and pyroptosis in hCSCs, and if attenuation of MMP9 improves viability of hCSCs." (PMID 32170070, 2020). "During hyperglycemia, the activity of MMP9 is increased and the degradation of the basement membrane is accelerated, which degrades the cell matrix in the basement membrane, loosens the cell structure, and provides nutrients and growth space for the formation of new blood vessels." (PMID 31892939, 2019). "Our results may suggest a possible up-regulation of MMP-9 in the setting of both acute and chronic hyperglycemia." (PMID 27110221, 2016). "Hyperglycemia induces intracellular ROS which upregulates the expression of MMP-9." (PMID 27803669, 2016). "Indeed, OC upregulation and control of expression of OPG, COL1A, and MMP-9 mRNAs, even in chronic hyperglycemia, support an anabolic and protective effect of zinc under chronic diabetic conditions." (PMID 25933189, 2015). "Reduced H3K9 methylation was also observed at the IL-1β and TNF-α promoters in LPS-treated THP-1 cells, at the MMP-9 promoter in phorbol 12-myristate 13-acetate–treated HeLa cells and at the NF-κB-p65 promoter in a model of transient hyperglycemia in bovine aortic endothelial cells." (PMID 24886859, 2014).